ENSG00000278454
Gene: Miscellaneous RNA gene on chromosome 8 (134,600,257 to 134,600,336, forward strand). Ensembl gene ENSG00000278454.
Gene Ontology:
Biological process: negative regulation of gene expression